DNAH7 (dynein axonemal heavy chain 7)
Description:
Force generating protein that plays an important role in respiratory cilia and sperm flagella beating. Produces force towards the minus ends of microtubules. Dynein has ATPase activity; the force-producing power stroke is thought to occur on release of ADP (By similarity).
Synonyms: KIAA0944; CILD50
Tractability: Small molecule: a structure with a bound ligand is known. PROTAC: ubiquitination databases record sites on it.
Gene: Protein-coding gene on chromosome 2 (195,737,703 to 196,068,837, reverse strand). Ensembl gene ENSG00000118997.
Subcellular location: Cytoplasm, cytoskeleton, cilium axoneme; Cell projection, cilium, flagellum
Subcellular location (Human Protein Atlas): Annulus; Mid piece; Cytosol; Vesicles
Gene Ontology:
Molecular function: dynein intermediate chain binding; dynein light intermediate chain binding; microtubule motor activity; minus-end-directed microtubule motor activity; ATP binding; calcium ion binding
Biological process: cilium movement; inner dynein arm assembly; cilium movement involved in cell motility; cilium-dependent cell motility; microtubule-based movement
Cellular component: cilium; inner dynein arm; sperm annulus; sperm midpiece; 9+2 motile cilium; axonemal dynein complex; axoneme; dynein complex; motile cilium; sperm flagellum
Genetic constraint (gnomAD): Loss-of-function variants: 348 observed, 395.62 expected, observed/expected ratio (o/e) 0.88, 90% interval 0.81 to 0.96. The upper end of that interval is the gene's LOEUF score, 0.96, which puts it in group 4 of 6, group 1 being the genes least tolerant of losing a copy. Missense variants: 4,524 observed, 4,590.1 expected, observed/expected ratio (o/e) 0.99, 90% interval 0.96 to 1.01. Synonymous variants: 1,522 observed, 1,559.6 expected, observed/expected ratio (o/e) 0.98, 90% interval 0.94 to 1.02.
Gene-disease validity (ClinGen):
ClinGen rates the evidence that DNAH7 causes each of these diseases.
primary ciliary dyskinesia (autosomal recessive): Limited. A rare, genetically heterogeneous, primarily respiratory disorder characterized by chronic upper and lower respiratory tract disease.
Homologues: Orthologues: chimpanzee DNAH7 (99% identical), macaque DNAH7 (98% identical), pig DNAH7 (93% identical), rabbit DNAH7 (92% identical), dog DNAH7 (92% identical), rat Dnah7 (90% identical), guinea pig DNAH7 (89% identical), mouse Dnah7b (89% identical), mouse Dnah7a (89% identical), mouse Dnah7c (89% identical), tropical clawed frog dnah7 (78% identical), zebrafish dnah7 (72% identical), and 1 more. Paralogues in human: DNAH12 (52% identical), DNAH3 (52% identical), DNAH1 (42% identical), DNAH6 (36% identical), DNAH2 (34% identical), DNAH10 (32% identical), DNAH17 (31% identical), DNAH9 (30% identical), DNAH11 (30% identical), DNAH14 (30% identical), DNAH8 (30% identical), DNAH5 (29% identical), and 3 more.
Diseases named in the same sentence as DNAH7 in open-access papers:
DNAH7 is named in the same sentence as 17 diseases in open-access papers, as found by Europe PMC text mining. Sharing a sentence is not in itself a finding about the gene and the disease. The quoted sentences say what the papers report.
primary ciliary dyskinesia (4 papers, 2017 to 2024). "DNAH7 variants are of interest because they encode a protein component of human cilia, where other functionally important mutations have been associated with primary ciliary dyskinesia (PCD)." (PMID 36920900, 2023). "Our literature searches identified 27 relevant papers for these genes, as well as two additional papers focused on two genes (ARMC4 and DNAH7, with UniProt IDs Q5T2S8 and Q8WXX0) that are also associated with primary ciliary dyskinesia." (PMID 29177046, 2017). "Besides, DNAH7 signal was undetectable in the cilia from primary ciliary dyskinesia cells." (PMID 32976492, 2020).
melanoma (3 papers, 2018 to 2021). A malignant, usually aggressive tumor composed of atypical, neoplastic melanocytes. "The top 10 mutated genes in melanoma were TTN (72%), MUC16 (67%), DNAH5 (49%), PCLO (44%), LRP1B (38%), ANK3 (32%), DNAH7 (32%), ADGRV1 (35%), RP1 (33%), and BRAF (51%)." (PMID 33758620, 2021). "The top 10 mutated genes in 467 melanoma patients are TTN (72%), MUC16 (67%), BRAF (51%), DNAH5 (49%), PCLO (44%), LRP1B (38%), ADGRV1 (35%), RP1 (33%), ANK3 (32%), DNAH7 (32%)." (PMID 33072607, 2020).
gastric cancer (1 paper, 2016). A primary or metastatic malignant neoplasm involving the stomach. "Genetic variations in other genes (e.g. KDM5A, DNAH7, PLCE1, PSCA, PRKAA1, MUC1) reported to be specifically associated with gastric cancer initiation and progression were not investigated in the current study." (PMID 27929383, 2016).
infertile (1 paper, 2024). "It has been demonstrated that infertile males with variants in DNAH1, DNAH2, DNAH7, and DNAH8 have a favorable prognosis, while patients with variants in DNAH17 have poor outcomes after ICSI treatment." (PMID 39503742, 2024).
testicular cancer (1 paper, 2020). A primary or metastatic malignant neoplasm that affects the testis. "In addition, DNAH7 was identified as novel susceptibility genes in testicular cancer." (PMID 32669100, 2020).
thromboembolic disease (1 paper, 2021). "The identified risk factors on chromosomes 2, 6, 7, 8, 10, 16, and 17 contain genetic variants and genes related to cilia dysfunctions (DNAH7 and CLUAP1), cardiovascular diseases (DES and SPEG), thromboembolic disease (STXBP5), mitochondrial dysfunctions (TOMM7), and innate immune system (WSB1)." (PMID 33536081, 2021).
infection (2 papers, 2021 to 2024). The state of being infected such as from the introduction of a foreign agent such as serum, vaccine, antigenic substance or organism. "The late decrease in transcripts encoding ciliogenesis regulators (FOXJ1, RFX3) and ciliary components (DNAH7) may in part result from the death of ciliated cells detectable at a more advanced stage of infection." (PMID 34272374, 2021). "Following infection of the bronchial epithelium with SARS-CoV-2, a reduction in the expression of cilia regulatory factors, including FOXJ1, RFX3, and DNAH7, was observed." (PMID 39195243, 2024).
DNAH7 also shares sentences with these, for which no sentence is quoted: cancer (3 papers); cardiovascular disease (2); tumor (2); cholesteatoma (1); colon cancer (1); COVID-19 (1); liver cancer (1); metabolic disease (1); Obesity (1); type 2 diabetes (1).